IL6 (interleukin 6)
Diseases named in the same sentence as IL6 in open-access papers (continued):
Sharing a sentence is not in itself a finding about the gene and the disease.
lymphedema (20 papers, 2009 to 2025). Excess fluid collection in tissues, causing swelling. "In particular, high IL-6 expression appears to associate with fat deposition in both lymphedema and obesity." (PMID 35450048, 2022). "IL-6, a known regulator of adipose tissue homeostasis, appears to be a negative regulator of adipose deposition in the setting of lymphedema as loss of IL-6 function resulted in increased adipose deposition in the tail surgery model of lymphedema in one study." (PMID 32268536, 2020). "Macrophages are also a major source of IL-6, a cytokine implicated in mediating chronic inflammation and adipose metabolism in lymphedema and found abundantly in lymphedema tissues." (PMID 30936872, 2019). "To determine the association of inflammatory cytokines with filarial lymphedema, we measured the plasma levels of IL-1β, IL-6, IL-12, and TNF-α in the four groups of subjects." (PMID 22685406, 2012). "Pro-inflammatory macrophages are recruited to the edematous tail tissues after surgery and aggravate lymphedema by inducing IL-6." (PMID 37540456, 2023). "In lymphedema, inflammatory fibrosis is first triggered at the cellular-molecular level via increased transcription of IL-6, IL-8, TNF-α, and TGF-β1." (PMID 36100619, 2022). "Meanwhile, studies on genetic predisposition of secondary lymphedema have demonstrated a significant association of VEGFR, RAR-related orphan receptor C (RORC), FOXC2, and interleukin-6 (IL6) genes with secondary lymphedema." (PMID 34733847, 2021). "Increased levels of IL-6 and leptin were observed in the serum of obese-lymphedema patients, probably reflecting the expansion of adipose tissue." (PMID 34733847, 2021). "To address the role of Th17 cells in filarial lymphedema, we examined the expression of IL-17A, IL-17F, IL-21 and IL-22 as well as the upstream inducing cytokines IL-23, IL-6 and IL-1β in PBMCs of lymphedema patients following BmA or PPD stimulation." (PMID 19381284, 2009). "Besides leptin, adipokines such as interleukin-6 have been reported to be increased in the serum in lymphedema patients to compensate for adipose tissue deposition as a response to chronic inflammation and lymphatic dysfunction." (PMID 36232660, 2022). "Interestingly, in the same study, it was shown that IL-6 is increased locally and systemically in patients with lymphedema, which was corroborated in animal models." (PMID 32268536, 2020). "Pre-surgery level of IL1-a, IL-6, IL-8, and VEGF was associated with the severe symptom class at 8 weeks post-surgery, suggesting that such biomarkers may be used to predict risk for lymphedema symptoms." (PMID 34322193, 2021). "Thus, regulating the level of leptin or IL-6 may be a viable strategy to reduce the incidence of postoperative lymphedema." (PMID 27366905, 2016). "In addition to weight control to reduce the serum level of leptin and leptin resistance, regulating the level of IL-6 may also be a viable strategy to treat postoperative lymphedema." (PMID 27366905, 2016). "Thus, regulating the level of leptin and/or IL-6 may reduce the incidence of postoperative lymphedema." (PMID 27366905, 2016). "In addition to immune cell activation, lymphedema tissue has dramatically higher levels of pro-inflammatory cytokines TNF-α, IL-6, IL-8, and MCP-1, which can be used to measure the inflammatory response." (PMID 37886950, 2023). "Lymphedema tissues also express increased proinflammatory cytokines such as TNF-α, IL-6, and IL-1β." (PMID 35450048, 2022). "Future studies are warranted to replicate our observation that differences in IL1-α, IL-6, IL-8, and VEGF levels and lymphedema symptoms and to evaluate levels of these biomarkers in relation to lymphedema symptom classes and arm lymphedema in an independent sample." (PMID 34322193, 2021).
lymphedema (continued). "Besides VEGF-C,VEGFR-3, and LTB4, infiltration of macrophages into the affected sites promotes the expression of cytokines and inflammatory factors including interleukins (IL-4, IL-6, IL-10), TNF-α, interferon-γ (IFN-γ), and transforming-growth factor-beta (TGF-β) in lymphedema studies." (PMID 34733847, 2021).
oral lichen planus (20 papers, 2012 to 2025). Oral lichen planus is a chronic inflammatory oral condition of unknown aetiology characterized by T-cell-mediated chronic immune response and abnormal epithelial keratinization cycle. "More recently, miR-155 was demonstrated as IL-6 and IL-8 regulator in oral lichen planus (OLS) associated-fibroblasts (OLP AFs)." (PMID 37945677, 2023). "Oral lichen planus (OLP) and chronic graft-versus-host disease (cGvHD) of the oral mucosa are inflammatory disorders associated with elevated local IL-6 levels." (PMID 41374963, 2025). "Altered levels of salivary cytokines IL-6 and TNFa have also been documented in recurrent aphthous ulcers and in oral lichen planus." (PMID 34884343, 2021). "The study by Zheng and co-workers found that P. melaninogenica can adhere to the cell surface, invade macrophages, and increase IL-1β, IL-6, and TNF-α expression in oral lichen planus." (PMID 37887710, 2023). "Salivary IL-6 levels are elevated not only in OSCC patients but also in chronic oral inflammatory diseases such as chronic periodontitis (CP) and oral lichen planus (OLP)." (PMID 36817607, 2023). "In studies conducted in USA, salivary IL6 and IL8 appeared as significant biomarkers of tongue OSCC, and as biomarkers that can monitor progression of oral lichen planus." (PMID 36900301, 2023). "It was revealed that IL-6 and TNF-α can promote malignant transformation in patients with oral submucous fibrosis and with oral lichen planus." (PMID 32245251, 2020).
proliferative diabetic retinopathy (20 papers, 2007 to 2025). Advanced retinopathy due to diabetes mellitus characterized by the formation of new vessels in the retina. "Subgroup analyses revealed a suggestive association between the GC genotype of IL-6-174 G/C with proliferative diabetic retinopathy (PDR)." (PMID 33060644, 2020). "Studies focusing on proliferative diabetic retinopathy observed notable associations of the two complement activation products complement 3a (C3a) and complement factor Ba (Ba) as well as VEGF and IL-6 within both ocular fluids." (PMID 40075380, 2025). "The levels of cytokines, including IL-1β, IL-6 and IL-8, are increased in the vitreous of patients with proliferative diabetic retinopathy and in the retina from diabetic rats and mice." (PMID 17437639, 2007). "As was demonstrated in another study, IL-6-174 G/C polymorphism was not connected to the ophthalmic diseases, while the GC genotype of IL-6-174 G/C was associated with proliferative diabetic retinopathy." (PMID 35163247, 2022). "IL-6 is a potent proinflammatory cytokine that may function in the pathogeneses of ocular neovascularization, such as proliferative diabetic retinopathy." (PMID 23826375, 2013). "Among those cytokines, the frequently reported cytokines such as TNF-α, IL-6, and TGF-β were compared between our study and proliferative diabetic retinopathy, and the expressions of the three cytokines in proliferative diabetic retinopathy were found times higher as compared with those in MH/ERM." (PMID 34336263, 2021). "Intraocular accumulation of IL6 is observed in proliferative diabetic retinopathy, although its involvement might not occur until the later stage of this disease." (PMID 33820928, 2021). "Our previous study also found that vitreous SAA and IL-6 levels in the eyes of proliferative diabetic retinopathy (PDR) patients were significantly higher than in nondiabetic patients, a result indicating that an inflammatory process may be involved in the development of PDR." (PMID 23861862, 2013).
retinal detachment (20 papers, 2011 to 2025). An eye emergency condition which may lead to blindness if left untreated. "For example, IL-1, IL-6, IL-8, and MCP-1 in the vitreous have been associated with retinal detachment and PVR." (PMID 38530532, 2024). "Although IL-6 is important for the photoreceptor survival during retinal detachment, it is also a critical factor for the EMT process in RPE cells and its levels are increased in the vitreous of PVR patients." (PMID 38530532, 2024). "On the other hand, studies in a rodent model of retinal detachment have demonstrated the neuroprotective properties of IL-6 against photoreceptors." (PMID 34069173, 2021). "To examine the consequences of blocking IL6 signaling in wild-type mice, we performed intravitreal injection of IL6 receptor antibodies immediately following retinal detachment." (PMID 28645275, 2017). "In our experiments, retinal IL6 protein expression was undetectable following retinal detachment, which is consistent with RNAseq data showing low IL6 gene expression." (PMID 28645275, 2017). "We evaluated MCP-1 and IL-6 expression levels by ELISA at 24 h after retinal detachment in the whole retina." (PMID 26583327, 2015). "This tendency was also observed in retinal detachment (RD) in IL-6−/− mice." (PMID 40308768, 2025). "Furthermore, osmolarity-activated TRPV4 increases the production of IL-1β and IL-6 in intervertebral disc cells; during acute retinal detachment-induced swelling of Müller cells, TRPV4 activation led to MCP-1 release and photoreceptor death." (PMID 34789280, 2021). "IL-6, in contrast, may also serve as a photoreceptor neuroprotectant, as was shown in an experimental model of retinal detachment." (PMID 21556354, 2011). "In addition, targeting IL-6 may help prevent recurrent fibrosis and retinal detachment." (PMID 40665980, 2025). "Positive correlations were found between the intraocular levels of several cytokines (IL-6, IL-8, MCP-1, ICAM-1, and ANG2) and CRT, NPAs, serous retinal detachment, and ME severity." (PMID 39272767, 2024). "Pro-inflammatory cytokines IL-6, IL-8, MCP-1, as well as VEGF have been detected in the vitreous of retinal detachment patients." (PMID 38530532, 2024). "Levels of HGF, IL-6, IL-8, IL-16, IFN-gamma, MCP-1, and MIF were significantly higher in all groups of retinal detachment compared to ERM." (PMID 32542038, 2020). "The concentrations of HGF, IFN-gamma, IL-6, IL-16, MIF, MCP-1 were significantly higher in all groups of retinal detachment compared to controls." (PMID 32542038, 2020). "Levels of HGF (p<0.0001), IFN-gamma (p<0.0001), IL-6 (p<0.0001), IL-16 (p<0.0001), MIF (p<0.0001), MCP-1 (p<0.0001) were significantly higher in all groups of retinal detachment compared to the group of ERM." (PMID 32542038, 2020). "Increased IL-6 levels are significantly associated with inner central retinal thickness (CRT), nonperfused areas, serous retinal detachment, and aqueous flare in RVO patients." (PMID 39272767, 2024). "However, Western blot analysis of aqueous humor and vitreous samples showed an increase in IL6 downstream effectors, p-STAT3 (9.26 fold, p < 0.01) and p-Erk1/2 (3.84 fold, p < 0.01) after retinal detachment (RD1)." (PMID 28645275, 2017). "It has been reported that these cytokines (IL-6, IL-8, and VEGF) may have a relationship with retinal detachment." (PMID 23049699, 2012). "Interestingly, IL-6, IL-8, and VEGF levels were also relatively high compared to other cytokines in the undiluted vitreous fluid of 6 rhegmatogenous retinal detachment eyes." (PMID 23049699, 2012). "The level of IL-6 did not significantly differ between diffuse retinal thickening (DRT), cystoid macular oedema (CMO), and serous retinal detachment (SRD) groups." (PMID 33060644, 2020). "Most cytokines concentrations (IL-2, IL-6, IL-8, IL-10, IL-17, TNF-α, IFN-γ, VEGF) were not statistically significant different compared to the rhegmatogenous retinal detachment control group except IL-1β." (PMID 23049699, 2012).
venous thromboembolism (20 papers, 2015 to 2025). Occlusion of the lumen of a vein by a thrombus that has migrated from a distal site via the blood stream. "Past works have found that CVD, and specifically CVI, is a condition associated with a venous thromboembolism, and IL-6 could be a potential link between those entities to be explored in future works." (PMID 39857734, 2025). "Increased IL-6 expression has been seen in the plasma of patients with a venous thromboembolism, which may play a vital role in inflammatory injury of vascular endothelial cells." (PMID 39857734, 2025). "The interplay between IL-6, IL-6 receptor antagonists, and venous thromboembolism is complex." (PMID 35203844, 2022). "The interplay between IL-6, IL-6 receptor antagonist, and venous thromboembolism is complex." (PMID 34178527, 2021). "The role of IL-6 in venous thromboembolism remains to be well defined." (PMID 33033405, 2020). "Patients with venous thromboembolism demonstrate increased levels of proinflammatory cytokines including interleukin-6, interleukin-8, and TNF-alpha and the formation of blood clots has been shown to lead to thrombus fragmentation and generation of proinflammatory fibrin breakdown products." (PMID 26078907, 2015). "IL-6 and TNF-α are familiar cytokines and some studies suggested that inflammation played a key role in the pathogenesis of venous thromboembolism." (PMID 36717769, 2023). "It aids in preventing venous thromboembolism, particularly in patients aged between 40 and 70 years, by inhibiting the mTOR cell pathway, suppressing platelet aggregation, and modulating immune responses, thereby reducing inflammatory markers such as TNF-alpha and IL-6." (PMID 40599143, 2025).
chronic pancreatitis (19 papers, 2013 to 2025). A chronic inflammatory process causing damage and fibrosis of the pancreatic parenchyma. "The expression of IL-1β and IL-6 was evaluated by immunohistochemistry on pancreata from patients with PDAC or chronic pancreatitis, or on normal human pancreas." (PMID 39260693, 2024). "It has also been confirmed that the level of IL-6 in PC patients was significantly elevated compared to that in patients with chronic pancreatitis." (PMID 37835869, 2023). "In this regard, the administration of AR-42 has been reported to suppress the transcriptional expression of pro-inflammatory cytokines, such as IL-1β, TNFα and IL-6, in trinitrobenzene sulfonic acid-induced chronic pancreatitis in mice." (PMID 37728477, 2023). "Interleukin-6 (IL6): This inflammatory marker is increased in chronic pancreatitis and PDAC, but importantly this increase is significantly higher in PDAC." (PMID 37760400, 2023). "We found that expression of the fibrosis marker GFAP, α-SMA and the inflammation marker TNF-α, IL-6 increased significantly in chronic pancreatitis when compared to controls." (PMID 32524326, 2020). "The study identified high levels of IL-6 in PDAC cases compared to chronic pancreatitis patients and elevated IL-10 and TNFα in PDAC cases compared to healthy subjects." (PMID 24884871, 2014). "In addition, we assessed the activation of PSCs by determining the levels of Col1a1, Mmp9, and Il6 factors previously shown to be upregulated in PSCs during chronic pancreatitis." (PMID 36835366, 2023). "In addition, we found a significant positive correlation between miR-301a expression and the expression of TGF-β and IL-6 in serum from patients with chronic pancreatitis." (PMID 35211358, 2022). "In conclusion, plasma YKL-40 and IL-6 alone are not useful as new diagnostic biomarkers to identify patients with PC at an early stage or to discriminate between patients with PC and chronic pancreatitis." (PMID 23840582, 2013). "On the other hand, IL-6 performed better than CA19-9 and CEA when used to discriminate PDAC patients from healthy and chronic pancreatitis individuals." (PMID 27170998, 2016). "Patients with chronic pancreatitis had significantly lower concentrations of all three biomarkers compared to patients with PC (all stages combined) (YKL-40 p = 0.047; IL-6 p<0.0001; CA 19-9 p<0.0001)." (PMID 23840582, 2013). "Patients with chronic pancreatitis had higher plasma YKL-40 (median 102 μg/l, 35% had elevated level compared to upper normal level), IL-6 (3.5 ng/l, 27%) and serum CA 19-9 (15 KU/l, 25%) compared to healthy subjects." (PMID 23840582, 2013). "Moreover, expression of miR-301a and two inflammatory factors, IL-6 and TGF-β, were also found to be significantly higher in serum of patients with chronic pancreatitis compared with healthy donors." (PMID 35211358, 2022). "The role of cytokines/chemokines in the pancreatic homeostasis may demonstrate among others studies on p38 mitogen-activated protein kinase which upregulates various cytokines and chemokines including IL-6, TNF-α, and MCP-1 and at the same time suppresses chronic pancreatitis." (PMID 31624954, 2019).